KLHL42 (kelch like family member 42)
Description:
Substrate-specific adapter of a BCR (BTB-CUL3-RBX1) E3 ubiquitin-protein ligase complex required for mitotic progression and cytokinesis. The BCR(KLHL42) E3 ubiquitin ligase complex mediates the ubiquitination and subsequent degradation of KATNA1. Involved in microtubule dynamics throughout mitosis.
Synonyms: Ctb9; KIAA1340; KLHDC5
Tractability: PROTAC: ubiquitination databases record sites on it; its protein half-life has been measured.
Gene: Protein-coding gene on chromosome 12 (27,780,000 to 27,803,040, forward strand). Ensembl gene ENSG00000087448.
Subcellular location: Cytoplasm; Cytoplasm, cytoskeleton, spindle
Pathways (Reactome):
Immune System: Antigen processing: Ubiquitination & Proteasome degradation
Metabolism of proteins: Neddylation
Gene Ontology:
Molecular function: protein binding; ubiquitin-protein transferase activity
Biological process: proteasome-mediated ubiquitin-dependent protein catabolic process; protein polyubiquitination; regulation of microtubule-based process; protein ubiquitination
Cellular component: Cul3-RING ubiquitin ligase complex; cytosol; cytoplasm; spindle
Genetic constraint (gnomAD): Loss-of-function variants: 22 observed, 23.76 expected, observed/expected ratio (o/e) 0.93, 90% interval 0.66 to 1.32. The upper end of that interval is the gene's LOEUF score, 1.32, which puts it in group 5 of 6, group 1 being the genes least tolerant of losing a copy. Missense variants: 368 observed, 450.13 expected, observed/expected ratio (o/e) 0.82, 90% interval 0.75 to 0.89. Synonymous variants: 212 observed, 202.87 expected, observed/expected ratio (o/e) 1.04, 90% interval 0.93 to 1.17.
Homologues: Orthologues: chimpanzee KLHL42 (100% identical), macaque KLHL42 (99% identical), dog KLHL42 (97% identical), pig KLHL42 (96% identical), rabbit KLHL42 (95% identical), mouse Klhl42 (91% identical), rat Klhl42 (90% identical), guinea pig KLHL42 (86% identical), zebrafish klhl42 (59% identical), tropical clawed frog klhl42 (46% identical). Paralogues in human: KBTBD11 (24% identical), KLHDC7B (23% identical), KLHDC7A (22% identical), KLHL13 (21% identical), KLHL9 (21% identical), KLHL14 (20% identical), KLHL32 (20% identical), KLHL36 (20% identical), KLHL28 (20% identical), KLHL5 (19% identical), KLHL22 (19% identical), KLHL34 (19% identical), and 42 more.
Diseases named in the same sentence as KLHL42 in open-access papers:
KLHL42 is named in the same sentence as 12 diseases in open-access papers, as found by Europe PMC text mining. Sharing a sentence is not in itself a finding about the gene and the disease. The quoted sentences say what the papers report.
breast carcinoma (2 papers, 2011 to 2024). "To further investigate the efficiency of A80.2HCl action on the MYC, KLHL42 and pRB1 axes identified in our study, we treated bladder cancer, prostate cancer and breast cancer cell lines with increasing doses of A80.2HCl." (PMID 38424044, 2024). "Moreover, a TCGA database analysis showed that KLHL42 mRNA was amplified in pancancer contexts, especially in breast cancer, bladder cancer and prostate cancer, and was significantly correlated with MYC protein levels in bladder cancer." (PMID 38424044, 2024).
atherosclerosis (1 paper, 2023). A disease characterized by the build-up of fatty material and calcium deposition in the arterial wall resulting in partial or complete occlusion of the arterial lumen. "The pathogenesis of atherosclerosis in which KLHL42 involves is needed for exploration." (PMID 36894991, 2023). "There is no other report correlates KLHL42 with atherosclerosis and vascular events." (PMID 36894991, 2023).
bladder cancer (1 paper, 2024). "Moreover, data from mouse tumors and human bladder cancer tissues confirmed the repression of pRB1 protein abundance mediated by MYC and KLHL42." (PMID 38424044, 2024).
tumor (2 papers, 2022 to 2024). "While a histological analysis indicated that Rb1 expression was markedly reduced in both normal and tumor specimens from the High Myc mice compared with the Pbsn-cre mice, the expression of Myc and Klhl42 was significantly increased in the High Myc mice." (PMID 38424044, 2024). "Collectively, these data described a novel pathogenesis where GATA3 overexpression further positively regulated KLHL42 expression and promoted tumor progression in CTCL when KLHL42 chromatin accessibility was high." (PMID 36400759, 2022). "Knocking down either KLHL42 or MYC-sensitized tumor cells to CDK4/6i treatment." (PMID 38424044, 2024). "Our study indicated that repressing of GATA3/KLHL42 axis might be one critical function route of 5-FU inhibiting tumor progression." (PMID 36400759, 2022). "Therefore, specific repression of KLHL42 by GATA3 might be one of the critical routes for 5-FU preventing tumor progression in CTCL." (PMID 36400759, 2022).
cancer (1 paper, 2024). A tumor composed of atypical neoplastic, often pleomorphic cells that invade other tissues. "Collectively, these results suggest that KLHL42 is a bona fide E3 ligase that modulates pRB1 protein ubiquitination and thus decreases pRB1 stability in cancers." (PMID 38424044, 2024). "Here, the authors show that MYC amplification induces CDK4/6 inhibitors resistance through transcriptional regulation of KLHL42, leading to RB1 degradation and targeting MYC overcomes CDK4/6 resistance in preclinical cancer models." (PMID 38424044, 2024). "High MYC expression activates the E3 ligase KLHL42, which is responsible for pRB1 ubiquitination and degradation and subsequently confers resistance to CDK4/6i to cancer cells." (PMID 38424044, 2024).
infection (1 paper, 2022). The state of being infected such as from the introduction of a foreign agent such as serum, vaccine, antigenic substance or organism. "The CeD-dominated cluster C1 differentially expressed genes including TRGC2, IKZF2, GPR18, TRDC and KLHL42 that are associated with ‘infection’ related response pathways including ‘NOD-like receptor signaling pathway’ in gene ontology analysis." (PMID 35995787, 2022).
lung (1 paper, 2024). "By performing a meta-analysis of published ChIP-seq datasets, we found an MYC-binding peak at the promoter of the KLHL42 gene in H2171 and SW1271 human lung cancer cells." (PMID 38424044, 2024).
KLHL42 also shares sentences with these, for which no sentence is quoted: diabetes (1 paper); lung adenocarcinoma (1); osteoporosis (1); prostate carcinoma (1); type 2 diabetes (1).